MCL1 (MCL1 apoptosis regulator, BCL2 family member)
Diseases named in the same sentence as MCL1 in open-access papers (continued):
Sharing a sentence is not in itself a finding about the gene and the disease.
small cell lung carcinoma (20 papers, 2013 to 2024). Small cell lung cancer (SCLC) is a highly aggressive malignant neoplasm, accounting for 10-15% of lung cancer cases, characterized byrapid growth, and early metastasis. "miRNA-26b suppresses tumorigenicity and promotes apoptosis by targeting the Mcl-1 protein in small-cell lung cancer (SCLC) cells." (PMID 35457012, 2022). "To identify the kinase(s) and the phosphorylation sites of MCL-1 induced by Noxa expression, we established stable expression of Flag-tagged human Noxa in H209 small cell lung cancer cells, in which the endogenous Noxa expression was undetectable." (PMID 27166195, 2016). "We also demonstrated a similar capability using a non-small-cell lung cancer cell line (PC9 cells), where we detected 8 different BCLxL- and MCL1 protein complexes using less than 50,000 PC9 cells each." (PMID 39025942, 2024). "Using small cell lung cancer (SCLC) as a model, we demonstrated the presence of differential addiction of cancer cells to anti-apoptotic BCL-2, BCL-XL or MCL-1, which correlated with the respective protein expression ratio." (PMID 28714472, 2017). "Actinomycin-D decreases Mcl-1 expression and acts synergistically with ABT-737 against small cell lung cancer cell lines." (PMID 26106377, 2015).
endometrial cancer (19 papers, 2007 to 2024). Primary or metastatic malignant neoplasm involving the endometrium (mucous membrane that lines the endometrial cavity). "Increased expressions of antiapoptotic Bcl-xL, survivin and Mcl-1 are strongly associated with the elevated p-Stat3 (Tyr705) in cervical and endometrial cancer tissues." (PMID 17311011, 2007). "Taken together, these results show marked combination activity through dual targeting the PI3K–AKT pathway and MCL1 signaling axes in the setting of endometrial cancer." (PMID 38456804, 2024). "Meanwhile, by sponging miR-216a, MEG3 enhances programmed death-1 (PD-1) expression while suppressing EMT inducer myeloid cell leukemia-1 (MCL-1) in endometrial cancer cells." (PMID 36551518, 2022). "A similar inhibitory mechanism between miR-101-3p and MCL-1 has been reported for endometrial cancer as well." (PMID 31864341, 2019). "Additionally, we observe inhibition of phospho ELK1 S383 at all time points and treatments, a mechanism previously shown to mediate sorafenib-induced endometrial carcinoma apoptosis by lowering MCL1 levels." (PMID 28157711, 2017). "The microRNA-101-EZH2/MCL-1/FOS axis is a potential therapeutic target for endometrial cancer." (PMID 25153722, 2014). "Ectopic expression of LRIG2 downregulated the pro-survival BCL-2 family members, including MCL-1, BCL-xL, BCL2A1, and BCL-2, whereas the pro-apoptotic BCL-2 family members, such as BAK, BAX, and BAD, were upregulated by LRIG2 in endometrial cancer cells." (PMID 29358688, 2018). "Although another study has indicated that miR-101 can suppress proliferation, migration and invasion, and stem cell-like phenotype of aggressive endometrial cancer cells, at least through targeting EZH2, MCL-1 and FOS." (PMID 29333128, 2017). "We have previously demonstrated the protective role of HURP (which acts upstream of survivin) and Mcl-1 against sorafenib in HCC and endometrial carcinoma cells, respectively." (PMID 26517516, 2015). "Especially, inhibition of LRIG2-induced cell death by ectopic expression of MCL-1 or by depletion of either BAK or BAX further support our conclusion that LRIG2 induces apoptosis in Hec-1A endometrial carcinoma cells by regulating the delicate equilibrium among the BCL-2 family of proteins." (PMID 29358688, 2018).
Thrombocytopenia (19 papers, 2014 to 2026). A reduction in the number of circulating thrombocytes. "Specifically, thrombocytopenia and cardiotoxicity are associated with Bcl-xL and Mcl-1 inhibition, respectively." (PMID 40849581, 2026). "To date, venetoclax (ABT-199) has already been approved for the clinic, while BCL-xL and MCL-1 inhibitors are showing clinical efficacy but may be associated with undesired secondary effects such as thrombocytopenia or cardiac toxicity, respectively." (PMID 40113795, 2025). "Direct targeting of MCL-1 or BCL-XL can restore the apoptotic threshold, but first-generation agents revealed safety ceilings: BCL-XL inhibitors (e.g., navitoclax) cause dose-limiting thrombocytopenia, and MCL-1 inhibitors show cardiac toxicity with continuous dosing." (PMID 41347170, 2025). "Direct targeting of MCL-1 or BCL-XL is feasible but limited by toxicities: early MCL-1 inhibitors showed cardiac safety signals, and BCL-XL blockade causes dose-limiting thrombocytopenia." (PMID 41347170, 2025). "For example, inhibition of BCL-XL results in thrombocytopenia, and inhibition of MCL-1 was reported to result in cardiac toxicity." (PMID 35201512, 2022). "However, the development of BH3-mimetics targeting BCL-XL or MCL1 has been more challenging, with on-target toxicities including thrombocytopenia for BCL-XL and cardiac toxicities for MCL1 inhibitors precluding clinical development." (PMID 40113751, 2025). "However, challenges to exploiting these vulnerabilities include thrombocytopenia caused by BCLXL inhibition, and the possible requirement for high concentrations of MCL1 antagonists, whose toxicity profile remains to be established." (PMID 32484436, 2020). "However, these inhibitors do not bind Mcl-1 with as high affinity, and their therapeutic potential is constrained by dose-limiting thrombocytopenia associated with potent Bcl-XL inhibition in platelets." (PMID 25285531, 2014). "MCL-1 is the preferred target, as agents such as Navitoclax that target both BCL-2 and BCL-XL, have resulted in platelet toxicity and dose limiting thrombocytopenia." (PMID 30701031, 2018). "These inhibitors efficiently reduce expression of MCL-1 and BCL-XL without causing severe toxicities such as thrombocytopenia, as they specifically target B cells." (PMID 35725771, 2022). "It is worth noting that thrombocytopenia was equivalent regardless of the type of diet, consistent with Mcl-1 not playing an essential role in platelet survival." (PMID 27689327, 2016).
viral infection (16 papers, 2010 to 2026). "Immunocompromised cancer patients already face high risks for infections; if treated with an Mcl-1 inhibitor, they might become even more susceptible to severe viral infections due to this “permissive” effect on viruses." (PMID 40951311, 2025). "Clinically, our results raise concerns regarding therapies that target Mcl-1, such as certain anticancer treatments, which may inadvertently increase susceptibility to severe viral infections." (PMID 40951311, 2025). "Infection with MCMV could replace Mcl-1 function in Mcl-1-deficient MEFs, suggesting that this is a common viral strategy, and implying that the loss of Mcl-1 protein or function is a common aspect of host cell defence against viral infection." (PMID 27537523, 2016). "It will be important to monitor viral infection rates or severity in patients receiving Mcl-1-targeting drugs and to ensure appropriate prophylactic measures (such as vaccinations or antiviral therapies) are in place." (PMID 40951311, 2025). "Specifically, MCL1 was significantly enriched in pathways related to viral infection, including hepatitis C, influenza A, measles, the RIG-I-like receptor signaling pathway, and the HIV-1 viral life cycle pathway." (PMID 40872527, 2025). "Research has shown that viral infections affect the intracellular amount of MCL-1 to modify the apoptotic potential of infected cells, fitting it to the “schedule” of the replication cycle." (PMID 38256213, 2024). "In vivo modeling using an MCL1 transgene demonstrated that T cells activated in response to viral infection shifted the population from short-lived effector cells to antigen-specific memory precursor cells." (PMID 34475520, 2021). "Ambiguous roles are found in non-viral diseases: miR-155 knockout mice are protected from Fas-induced liver injury by activating the anti-apoptotic survival factor MCL-1 (myeloid cell leukemia 1)." (PMID 29921785, 2018). "Although further studies are needed to clarify the molecular mechanisms, the translational suppression induced by viral infection is suggested to participate in the instability of unstable proteins including MCL1." (PMID 30261081, 2018). "To test for the relative roles of Mcl-1 and Bcl-XL in macrophages during viral infection, we used cells derived from mice carrying the respective alleles flanked by cre-lox-recognition sites together with Cre under the LysM promoter." (PMID 27537523, 2016). "In cells with a reduced translational capacity due to nutrient deprivation, stress or viral infection, Mcl-1 protein levels are markedly reduced." (PMID 20152035, 2010). "MCL1, a key anti-apoptotic member of the Bcl-2 family, plays a dual role during viral infections." (PMID 40872527, 2025). "Notably, Mcl-1 and Bcl-XL have been described as guards of host translation during viral infection of keratinocytes." (PMID 40530878, 2025). "The investigation of the cellular and molecular mechanisms involved in viral infections engaging MCL1 may contribute to a better understanding of the regulation of cell death and survival balance." (PMID 38256213, 2024). "Although this may be the case in the circumstance of viral infection, Mcl-1 has a much broader activity in terms of binding specificity for pro-apoptotic Bcl-2 family proteins." (PMID 21698224, 2011). "Furthermore, understanding the biology of MCL-1 and other anti-apoptotic BCL-2 family proteins during viral infections may help to explore the therapeutic rationale for MCL-1 inhibitors as a novel treatment for human cancers and other diseases." (PMID 38256213, 2024). "In addition, viral infection decreased MCL1 expression in a variety of human and murine cell lines." (PMID 30261081, 2018). "Although not generally applicable, the loss of Mcl-1 may be a more general defence mechanism of mammalian cells attempting to undergo apoptosis upon viral infection." (PMID 27537523, 2016).
viral infection (continued). "KEGG and GO enrichment analyses further confirm that MCL1 predominantly operates through the PI3K-Akt-GSK-3 axis and Toll-like receptor signaling to regulate apoptosis and maintain immune homeostasis during viral infection." (PMID 40872527, 2025). "Resveratrol affects the phosphorylation status of STAT3 and indirectly downregulates the level of MCL-1 in HTLV-positive ATLL cells, abolishing the prosurvival effect of viral infection." (PMID 38256213, 2024). "During viral infections (including RSV), host cells often upregulate Mcl-1." (PMID 40951311, 2025). "At the gene level, we found that NF could significantly induce a set of ISG expressions, such as MCL1, IFITM3, B2M, BST2, OAS1, and PKR to function against virus infection." (PMID 35910807, 2022). "The findings suggest that during viral infection of macrophages a pro-apoptotic activity is generated that is to a substantial degree blocked by Bcl-XL but not by Mcl-1." (PMID 27537523, 2016). "A deeper understanding of Mcl-1’s role in RSV and other viral infections will improve our knowledge of viral pathogenesis and could inform the development of therapies that carefully consider the balance between controlling cancer and maintaining antiviral defenses." (PMID 40951311, 2025). "In macrophages, apoptotic stimuli may therefore rely more heavily on pathways not involving Mcl-1, and viral infection may be one such stimulus." (PMID 27537523, 2016).
Burkitt lymphoma (14 papers, 2012 to 2023). A rare form of malignant mature B-cell non-Hodgkin lymphoma. "Phosphorylation at Thr 163 in the PEST region, stimulated by 12-O-tetradecanoylphorbol acetic acid (TPA)-induced activation of extracellular signal-regulated kinase (ERK), is associated with Mcl-1 stabilization in BL41-3 Burkitt lymphoma cells." (PMID 23056582, 2012). "A recent study revealed that c-MYC-driven human Burkitt lymphoma cells were eradicated by targeting MCL-1." (PMID 37570631, 2023). "For example, myeloid leukemia cell differentiation protein (MCL1), an antiapoptotic protein, is essential for the sustained survival of human Burkitt lymphoma (BL) cells." (PMID 31687377, 2019). "We previously showed that isofistularin-3 induced endoplasmic reticulum (ER) stress in RAJI Burkitt lymphoma cells and ER stress-inducing agents were shown to lower Mcl-1 levels." (PMID 30572618, 2018). "Mcl-1 is also regulated post-translationally, as observed in the BL41-3 Burkitt lymphoma cell line in which endogenous Mcl-1 is amplified and overexpressed." (PMID 23056582, 2012). "SYK inhibition lowers viability and Mcl-1 protein levels in Burkitt’s lymphoma cell lines." (PMID 29740433, 2018). "Burkitt lymphoma (inherently BCL2-negative) and a subset of BCL2-negative DLBCL are strongly dependent on MCL1 for survival." (PMID 34576319, 2021). "Similar profiles for Mcl-1 and viability following SYK inhibition in the presence of Q-VD-Oph were observed with the Burkitt’s lymphoma cell lines RAMOS and BL2." (PMID 29740433, 2018). "Human and mouse tumour cells driven by deregulated over-expression of c-MYC are highly dependent on the anti-apoptotic protein MCL-1 for survival and the MCL-1-specific BH3 mimetic drug S63845 induces dose dependent apoptotic death in murine Eμ-Myc as well as human Burkitt’s lymphoma cell lines." (PMID 32555451, 2020). "In translation, all BCL2-negative malignancies (e.g., Burkitt lymphoma, BCL2-negative DLBCL, or a substantial part of MM) are inherently “resistant” to BCL2 inhibition with venetoclax but still may be effectively targeted with other BH3 mimetics, e.g., MCL1 inhibitors." (PMID 34576319, 2021). "The Burkitt’s lymphoma cell line Ramos, which is also characterized by MYC translocation and expression of Mcl‐1 but not BCL2, showed a similar sensitivity profile." (PMID 34632715, 2022). "Notably, MCL-1 plays an oncogenic role in regulating the survival and tumorigenicity of PEL cells but not in Burkitt‘s lymphoma cells (e.g., BJAB)." (PMID 33471866, 2021).
heart failure (14 papers, 2013 to 2025). Inability of the heart to pump blood at an adequate rate to meet tissue metabolic requirements. "Heart failure is often associated with an accumulation of dysfunctional mitochondria and the death of myocytes, and therapeutic targeting of Mcl-1 has already shown promise in other disease contexts." (PMID 35563775, 2022). "Loss of Mcl-1 has previously been shown to result in cardiomyopathy and impaired autophagy leading to heart failure in mice." (PMID 30281024, 2018). "Mcl-1 is involved in cardiomyocyte loss and contributes to a variety of cardiac pathologies, including heart failure and ischemia/reperfusion injury." (PMID 28491238, 2017). "MCL-1 is a critical molecule for cardiomyocyte survival, since ablation of cardiac specific MCL-1 causes fatal heart failure and significant mitochondrial damage." (PMID 26691397, 2015). "Mcl-1 is essential for cardiac homeostasis, and deletion of Mcl-1 in myocytes leads to the rapid development of heart failure despite little activation of apoptosis, demonstrating the importance of its other functions." (PMID 35563775, 2022). "In order to demonstrate the role of Mcl1 in heart failure, we generated hypertrophic mice infused with Ang II for 6 weeks." (PMID 33469534, 2020). "The cardiac toxicity seen in patients being treated with AMG 397 represents a considerable concern for heart failure as a side effect of Mcl-1 inhibition and will need to be addressed if direct Mcl-1 inhibition is to be utilized clinically." (PMID 33335095, 2020). "Myeloid cell leukemia 1 (Mcl1), an abundant protein in the myocardium, plays an essential role in fibrosis and anti-inflammation in cardiomyocytes to prevent heart failure." (PMID 33469534, 2020). "For example, MCL-1 has been shown to have an essential role in basal myocyte homeostasis and ablation of MCL-1 in adult myocytes results in mitochondrial dysfunction, impaired autophagy and consequently rapid development of heart failure." (PMID 27140313, 2016). "It was reported that deletion of Mcl-1 gene leads to cardiomyocyte disorganization, fibrosis, inflammation, and lethal heart failure." (PMID 25062042, 2014). "Although these studies did not evaluate the role of Mcl-1 and ROS in cardiac injury, other models of heart failure have demonstrated this association." (PMID 28423654, 2017). "Recent studies have highlighted the importance of MCL-1 in preventing heart failure." (PMID 25062042, 2014). "More relevant to Mcl-1 biology, the absence of Mcl-1 in cardiac tissue specific mouse genetic knock-out models is associated with abnormal mitochondrial function, inability to regulate autophagy, and cardiac failure." (PMID 28423654, 2017). "However, conditional deletion of MCL-1 in mice induced heart failure in a BAK- and BAX-dependent process, raising concerns for cardiac toxicity with MCL-1 inhibitors." (PMID 34065859, 2021).
nasopharyngeal carcinoma (13 papers, 2014 to 2022). A carcinoma arising from the nasopharyngeal epithelium. "Radiation-induced stemness and radioresistance in nasopharyngeal carcinoma (NPC) largely depended on the upregulation of MCL-1 protein, which was attributed to intracellular reactive oxygen species and Akt activation following repeated ionizing radiation." (PMID 36535926, 2022). "Over-expression of BCL-2 and related family proteins (BCL-xL and MCL-1) confers anti-apoptotic response and contributes to the development of resistance to chemotherapy and radiation treatment for nasopharyngeal carcinoma (NPC)." (PMID 34064109, 2021). "The combined use of TVA and Mcl-1 inhibitors offers a potential advantage for nasopharyngeal cancer treatment." (PMID 30738430, 2019). "Thus, the combined use of TVA and Mcl-1 inhibitors is a promising prospect for nasopharyngeal cancer treatment." (PMID 30738430, 2019). "Indeed, in a previous study, CCB induced apoptosis by inhibiting the expressions of p-STAT3 and Mcl-1 in nasopharyngeal carcinoma cells." (PMID 29541415, 2018). "For example, in nasopharyngeal carcinoma (NPC), CRISPR/Cas9 screening associated to the use of BH3-mimetic drugs helped the identification of those crucial proteins that play an antiapoptotic role in NPC-related treatment resistance, namely BCL-XL, MCL-1 and BFL-1." (PMID 36497228, 2022). "In this study, we tested the sensitivity of two Nasopharyngeal Carcinoma (NPC) cell lines HK1 and C666-1 to Maritoclax, which is reported to repress anti-apoptotic protein MCL-1 and BH3 mimetic ABT-263, which selectively inhibits anti-apoptotic proteins BCL-2, BCL-XL and BCL-w." (PMID 33214852, 2020).
esophageal squamous cell carcinoma (12 papers, 2014 to 2023). Esophageal squamous cell carcinoma (ESCC) is a type of esophageal carcinoma (EC) that can affect any part of the esophagus, but is usually located in the upper or middle third. "Dual inhibition of the PI3K/AKT/mTOR pathway with MK2206 and BEZ235 caused cell cycle arrest and enhanced apoptosis through the downstream effectors SKP2, MCL-1, and cyclin D1 in esophageal squamous cell carcinoma cells." (PMID 33659215, 2020). "Re-expression of cDOPEY2 decreases the expression of the anti-apoptotic protein Mcl-1 and substantially strengthens the cell lethality of CDDP by augmenting the apoptotic process in CDDP-resistant esophageal squamous cell carcinoma (ESCC) cells." (PMID 35070998, 2021). "However, the role of MCL1 gain has not yet been determined in esophageal squamous cell carcinomas (ESCC)." (PMID 29152113, 2017).